MTOR (mechanistic target of rapamycin kinase)
Diseases named in the same sentence as MTOR in open-access papers (continued):
Sharing a sentence is not in itself a finding about the gene and the disease.
hepatocellular carcinoma (continued). "In hepatocellular carcinoma, celecoxib inhibited PNO1 expression and tumour growth through modulation of AKT/mTOR signalling pathway." (PMID 36625087, 2023). "Activation of the mTOR signaling pathway, a branch downstream of AMPK, plays an essential role in the occurrence and progression of cancer, primarily hepatocellular carcinoma." (PMID 38192642, 2023). "In this study, H22 hepatoma cells treated with B. coagulans MZY531 showed a concentration-dependent reduction in the expression of p-PI3K, p-AKT and p-mTOR compared to the control group." (PMID 37705007, 2023). "In hepatocellular carcinoma, knockdown of BCAT1 or administration of leucine activated mTOR signaling, inhibited autophagy, and increased cisplatin sensitivity and percentage of cell apoptosis." (PMID 36163180, 2022). "In vascular endothelial cells, inhibition of mTOR by rapamycin decreases the expression of DNMT1, while in hepatocellular carcinoma cell lines Hep G2, SNU-182, and Hep 3B2.1-7, inhibition of mTOR with Torin-2 increases the expression of DNMT1." (PMID 36430934, 2022). "Oncological follow-up may benefit from tumor-inhibiting properties of mTOR inhibitors (mTORI), shown with improved survival for recurrent hepatocellular carcinoma (HCC) patients after LT." (PMID 35740555, 2022). "In the HepG2 hepatoma cell line, hexanoic acid was found to regulate the PI3K/Akt/mTOR pathway, which is required for inducing lipid metabolism in this cell type." (PMID 35902806, 2022). "Furthermore, SLFN11 suppresses the proliferation of hepatocellular cancer cells by interacting with the ribosomal protein S4 X-linked (RPS4X), resulting in attenuation of S6 and eIF4E phosphorylation in the ribosome complex and inhibition of the mTOR signaling pathway." (PMID 35768579, 2022). "The sucessful tumor cell integration of these multi-functionalized nanoparticles proved to drastically suppress tumorigenesis by targeting mTOR, PAK4, RHOC, and the epithelial–mesenchymal transition (EMT) in hepatocellular carcinoma (HCC) PDX models." (PMID 35954481, 2022). "Especially the PI3K/AKT/mTOR pathway that performs an essential effect on the tumorigenesis of HCC including proliferation, metastasis, and resistance to chemotherapy, any alterations of the PI3K/AKT/mTOR pathway could cause pathological processes of hepatocellular carcinoma." (PMID 35592706, 2022). "In hepatocellular carcinoma, the replenishment of miR-486-5p blocks the IGF-1R pathway by acting on the downstream mediators such as mTOR, STAT3, and c-myc." (PMID 35337095, 2022). "In hepatocellular carcinoma, RPS4X is required for SLFN11 inactivation in the mTOR signaling pathway." (PMID 36474171, 2022). "Isoviolanthin isolated from Dendrobium officinale reverses TGF-β1-mediated epithelial-mesenchymal transition in hepatocellular carcinoma (HCC) cells by deactivating the TGF-β/Smad and PI3K/Akt/mTOR signalling pathways." (PMID 35159021, 2022). "In hepatocellular carcinoma, ADAMTS9-AS1 triggered PI3K/AKT/mTOR pathway of liver cancer cells, exacerbated cell proliferation and migration." (PMID 35311457, 2022). "Our results suggested that the FAK/PI3K/AKT/mTOR pathway affects the activities and expressions of MMP-2 and MMP-9, further inhibiting the migration and invasion of hepatocellular carcinoma cells." (PMID 36483979, 2022). "Collectively, 4-AAQB inhibits hepatoma cells proliferation and metastasis via suppressing PI3K/Akt/mTOR, ERK pathways and inhibition of Rho GTPase signaling pathway via suppressing VEGF production." (PMID 35678690, 2022). "The E2F1/USP11 positive feedback loop promotes hepatocellular carcinoma metastasis and inhibits autophagy by activating the ERK/mTOR pathway." (PMID 35383175, 2022). "The mTOR gene, involved in the induction stages of autophagy, has been described as the target of several miRNAs, including miR-100, which has been shown to directly suppress the expression of mTOR, thus inducing autophagy in hepatocellular carcinoma cells (HCC)." (PMID 36143432, 2022).
hepatocellular carcinoma (continued). "In particular, ADAMTS9-AS1 is highly expressed in hepatocellular carcinoma cells and it exacerbates cell proliferation, migration and invasion through the PI3K/AKT/mTOR pathways." (PMID 36338971, 2022). "This study explored the effects of Hugan Buzure (HBR) on cell apoptosis and autophagy in hepatocellular carcinoma (HCC) and the molecular mechanisms of the PI3K/Akt/mTOR signaling pathway." (PMID 38094222, 2022). "Under increased substrate stiffness, hepatocellular carcinoma cells (HCC) demonstrate enhanced features of stemness and upregulation of Akt, mTOR, 4E-BP, and SRY (sex-determining region Y)-box 2 (SOX2) phosphorylation." (PMID 35163745, 2022). "In hepatocellular carcinoma, miR‐19a downregulates PTEN, and consequently, these cells have increased cell growth rates as AKT is a major player in cell proliferation via mTOR signaling." (PMID 35417090, 2022). "In hepatocellular carcinoma, TRIP13 regulated by miR-192-5p was shown to interact with and increase the expression of actinin alpha 4 (ACTN4), thus activating the AKT/mammalian target of rapamycin (mTOR) pathway to drive tumor progression." (PMID 36268276, 2022). "AFP can activate the PI3K/AKT signalling, stimulates the transcription cofactor mTOR, STAT3, HIF‐1α and Bcl‐2, which regulates the expression of oncogenes, as well as promotes angiogenesis and the growth of the hepatoma cells." (PMID 36181321, 2022). "UBE2O promotes hepatocellular carcinoma cell proliferation and invasion by regulating the AMPK/mTOR pathway." (PMID 36185617, 2022). "Previous studies reported that SHMT2 can promote liver regeneration through the glycine-activated Akt/mTOR pathway, while a downregulated SHMT2 can suppress tumorigenesis in human hepatocellular carcinoma." (PMID 34149818, 2021). "Consistently, in other hepatoma cell lines, knockdown of ENDOG increased phosphorylation of mTOR and ULK1, as well as suppressed autophagy under starvation." (PMID 33473107, 2021). "Additionally, isoviolanthin was revealed to suppress transforming growth factor (TGF)-β1-induced EMT through the regulation of TGF-β/Smad and PI3K/Akt/mTOR signaling pathways in HepG2 and Bel-7402 hepatocellular carcinoma (HCC) cells." (PMID 34421620, 2021). "In our study, the signal pathways enriched for DEGs are mostly related to the small-molecule metabolic pathways and cancer-related signal pathways such as the mTOR signaling pathway, hepatocellular carcinoma, TNF signaling pathway, and mTOR signaling pathway." (PMID 34504838, 2021). "Our study showed that miR-149 overexpression reduced protein levels of Akt, p-Akt, mTOR, and p-mTOR in ox-LDL-induced HUVECs, which is consistent with the results in another report in human hepatocellular carcinoma (HCC) cells." (PMID 34484820, 2021). "For example, lncRNA MALAT1 promoted hepatocellular carcinoma development by regulating SRSF1 and activating mTOR signaling." (PMID 34240756, 2021). "The genetic disruption or chemical inhibition of SLC3A2/ SLC7A11 HATC leads to autophagy and ferroptosis in the different types of tumor cells, including endometrial, colorectal, pancreatic cancer, and hepatocellular carcinoma (HCC) through inhibition of mTOR/p70S6K signaling." (PMID 33401748, 2021). "FASN has been previously reported to promote carcinogenesis by activating mTOR, a master negative regulator of autophagy, via AKT signaling in hepatocellular carcinoma." (PMID 33742137, 2021). "Herein, we investigated the inhibitory effects of 4-HD on hepatocellular carcinoma (HCC) cells and clarified the potential mechanisms by exploring apoptosis and cell cycle arrest mediated via the PI3K/AKT/mTOR signaling pathway." (PMID 34574146, 2021). "Moreover, GSK-3β regulates mTOR activity as well as in cancer research in hepatocellular carcinoma (HCC)." (PMID 35095838, 2021). "Specifically, triggering the PI3K/Akt/mTOR signaling pathway directly inhibits the transcription of HBV 3.5-kb and 2.4-kb RNA and HBV replication in hepatoma cells." (PMID 34580816, 2021).
hepatocellular carcinoma (continued). "As OA also inhibited AMPK and activated mTOR in human hepatocellular carcinoma (HCC) cells, as found for rat hepatocytes, the authors stated that humans could also be susceptible to OA-induced fatty liver." (PMID 32284043, 2020). "Our results indicated that the combination of biochanin A and SB590885 suppressed the growth of hepatocellular carcinoma cells via inhibition of the ERK MAPK and PI3K/AKT/mTOR signalling pathways." (PMID 32774165, 2020). "MK-2206 had synergetic effects with other mTOR inhibitors like RAD001 in cholangiocarcinoma and hepatocellular carcinoma." (PMID 32116708, 2020). "Inhibiting of Na +/K+-ATPase pump suppresses hepatoma cell adhesion, migration, and invasion through inhibition of PI3K/AKT/mTOR pathway." (PMID 32054977, 2020). "Further, there are many pathways that baicalein can fight against hepatocellular carcinoma, such as MAPK and NF-κB pathway, ERK pathway, Akt/mammalian/mechanistic target of rapamycin (mTOR) pathway, etc.." (PMID 33265939, 2020). "In conclusion, miR-100 and miR-125b have tumor suppressor role in hepatocellular carcinoma through inhibiting IGF2 expression and activation of the AKT/mTOR pathway." (PMID 33293585, 2020). "As SC66 is reported to inhibit Akt in hepatocellular carcinoma cells, we tested AKT and mTOR signaling in SC66-treated RCC cells." (PMID 32393791, 2020). "Similarly, the reversal effect of vitamin D has been also observed in several hepatocellular carcinoma (HCC) cell lines resistant to everolimus, an mTOR inhibitor." (PMID 32560347, 2020). "Previous studies have reported that isoviolanthin, a C-glycoside flavonoid with apigenin as the parent nucleus, inhibits TGF-β1-induced EMT in hepatocellular carcinoma cells via the deactivation of the TGF-β/Smad and PI3K/Akt/mTOR signaling pathways." (PMID 30609689, 2019). "In summary, our study demonstrated the preclinical activity of PH, which inhibits hepatic carcinoma in vitro and in vivo and prolonged mouse survival via molecular targeting of STAT3/Akt/mTOR/JAK2/VEGF2 pathways." (PMID 31619257, 2019). "The combination of PI3K/mTOR inhibitor CMG002 with sorafenib inhibited proliferation of hepatocellular carcinoma cell lines, induced apoptosis and blocked the activity of both Ras/MAPK and PI3K/mTOR pathways." (PMID 31817676, 2019). "For instances, apigenin can inhibit the proliferation of hepatoma cells and induce autophagy by inhibiting the PI3K/AKT/mTOR pathway." (PMID 31835352, 2019). "For instance, Glycochenodeoxycholate can promote hepatocellular carcinoma invasion and migration by AMPK/mTOR dependent autophagy activation." (PMID 31835352, 2019). "It has been reported that miR-149-5p can inhibit cell proliferation, invasion and migration in human hepatocellular carcinoma by targeting AKT1 and further facilitating the mTOR pathway." (PMID 30717751, 2019). "For example, miRNA-99b-5p suppresses liver metastasis of colorectal cancer by down-regulating mTOR, and miR-203a suppresses cell metastasis and angiogenesis through VEGFR by targeting HOXD3 in human hepatocellular carcinoma cells." (PMID 29973668, 2018). "Bufalin increasing the sensitivity to mTOR-induced autophagy has been previously proved in human hepatocellular carcinoma cells, and arenobufagin induces apoptosis and autophagy via inhibiting PI3K/Akt/mTOR." (PMID 30108651, 2018). "Huaier granules can also increase the sensitivity of human hepatoma cell lines SKHEP-1 and HepG2 to rapamycin and cisplatin and thus enhance the anti-tumor effect of chemotherapeutics, probably by activating thr mTOR pathway." (PMID 30524272, 2018). "Likewise, p-mTOR staining was more diffuse and stronger in metastatic hepatocellular carcinoma (HCC) than in primary HCC." (PMID 28831205, 2017).
hepatocellular carcinoma (continued). "In conclusion, the present study demonstrated that Purslane exhibited protective effect on NDEA-induced hepatocellular carcinomas by inhibiting inflammatory response and oxidative stress possibly through the PI3K/AKT/mTOR and Nrf2/HO-1/NF-κB pathway." (PMID 28659990, 2017). "In hepatocellular carcinoma (HCC) cells, miR-7 was also introduced as a key regulator of the PI3K/Akt pathway, and shown to target mTOR, p70S6K, and PIK3CD." (PMID 28459042, 2017). "In patients with HCC and human hepatoma cell lines, overexpression of IGF-IR and mTOR were observed." (PMID 28624790, 2017). "Our previous study of Huh-7 hepatoma cells showed that exposure to 7-KC increased the efflux function and the protein level of P-gp through the phosphatidylinositol 3-kinase (PI3K)/mammalian target of rapamycin (mTOR) phosphorylation signaling pathway." (PMID 29029490, 2017). "In conclusion, our research suggested that Purslane exhibited protective effects on NDEA-induced hepatocellular carcinomas by anti-inflammatory and antioxidative properties via the PI3K/Akt/mTOR and Nrf2/HO-1/NF-κB pathway." (PMID 28659990, 2017). "The combination of PI-103 and sorafenib was found to inhibit hepatocellular carcinoma cell proliferation by blocking Ras/Raf/MAPK and PI3K/AKT/mTOR pathways." (PMID 28415592, 2017). "It is interesting that inhibition of Akt/mTOR signaling in concurrence with enhanced ERK1/2 activity exists in GL‐induced autophagy and cytotoxicity in HepG2 and MHCC97‐H hepatocellular carcinoma cells." (PMID 28675698, 2017). "In hepatocellular carcinoma, TRAF4 regulates migration, invasion, and the EMT process via PI3K/Akt/mTOR signaling pathway." (PMID 28864782, 2017). "In HepG2 cells, a human hepatoma cell line, AQP9 was found to be up-regulated by insulin through the phosphatidylinositol 3-kinase/protein kinase B/mammalian target of rapamycin (PI3K/Akt/mTOR) signaling cascade." (PMID 27409609, 2016). "Deregulation of mTOR and IGF pathways is frequent in hepatocellular carcinoma (HCC), thus mTOR and IGF1R represent suitable therapeutic targets in HCC." (PMID 26756219, 2016). "On the other hand, bufalin stopped the proliferation of hepatocellular carcinoma by activating autophagy through the Akt/mTOR and AMPK/mTOR pathways respectively." (PMID 26999089, 2016). "Several studies have reported that simvastatin inhibits adhesion and invasion in leukemias, hepatocellular cancer, melanoma and endometrial cancer through multiple cell signaling pathways such as the ROCK, MAPK and mTOR pathways." (PMID 26503475, 2016). "The novel PI3K/mTOR inhibitors, GDC-0980, GDC-0941 and PF-04691502 have been reported to induce G1 cell-cycle arrest in breast, lung, glioblastoma and hepatocellular carcinoma cells." (PMID 26506516, 2015). "Adiponectin inhibits hepatocellular carcinoma by increasing phosphorylation of c-Jun-N-terminal kinase (JNK) and inhibiting mammalian target of rapamycin (mTOR) phosphorylation." (PMID 25051362, 2014). "Because mammalian target of rapamycin (mTOR) is downstream effector of Akt, we utilized rapamycin, a mTOR inhibitor, and found rapamycin also suppressed PGE2-stimulated sphere formation in hepatoma cells." (PMID 24721996, 2014). "We established human hepatoma Hep 3Bx and Hep G2x cell lines which stably express HBx to investigate the effects of HBx overexpression on IKKβ/TSC1/mTOR signaling." (PMID 22848663, 2012). "In this study, we aimed to investigate the PI3K/AKT/mTOR signaling pathway in hepatocellular carcinoma by highlighting the feedback activation of AKT and its distinct isoforms following mTOR inhibition by RAD001." (PMID 23167739, 2012).